TSLP (thymic stromal lymphopoietin)
Diseases named in the same sentence as TSLP in open-access papers (continued):
Sharing a sentence is not in itself a finding about the gene and the disease.
viral infection (continued). "On the other hand, IL-25, IL-33, and thymic stromal lymphopoietin (TSLP), which are mainly secreted from the airway epithelium due to Alternaria, protease activity of antigens such as HDM, and fungus and viral infection, are also involved in type 2 immunity." (PMID 32397396, 2020). "A study suggests the preventive role of the measles vaccine in order to downregulate TSLP production, but no clear link has been established between AD and virus infections." (PMID 34944487, 2021). "TSLP has been studied extensively in the context of TH2-type immunity, and we previously demonstrated that TSLP can act directly on CD4+ and CD8+ T cells, but its roles in CD8+ T cell responses during viral infection remain poorly understood." (PMID 33439121, 2021). "After a baby is exposed to more environmental LPS, which is relatively nonpathogenic, then when it later encounters a common viral infection, the dsRNA cannot activate the epithelial cells to produce allergic cytokines, such as TSLP, IL33 and IL25." (PMID 29065558, 2017). "As previously shown, TSLP mRNA expression was not increased by viral infection." (PMID 38061015, 2024). "However, a direct role for TSLP in CD8+ T-cell primary responses remains controversial and its role in memory CD8+ T cell responses to secondary viral infection is unknown." (PMID 33439121, 2021). "CRSwNP epithelial cells release TSLP and IL-25 when stimulated by poly(I:C) but not by DP or AF, suggesting that viral infection may contribute to maintain and amplify the T2 immune response seen in CRSwNP." (PMID 28127565, 2016). "Therefore, the temporality of plasma TSLP levels between the initial virus infection and the day of hospitalization could not be determined." (PMID 36851770, 2023). "Thus, the inhibitory effects on TSLP and CCL26 expression even after viral infection are not common among glucocorticosteroid species, but linked with the pharmacological property of BUD." (PMID 32120846, 2020). "LPS, or maybe farm dust, attenuates the induction of proallergic cytokines, including TSLP, IL33, and others in respiratory epithelial cells in response to viral infection, and it does not disturb the Th1-prone effect of viruses on DCs." (PMID 29065558, 2017).
nasal polyps (40 papers, 2012 to 2026). "Increased DNA methylation of TSLP locus is also associated with pathogenesis of chronic rhinosinusitis patients with nasal polyps." (PMID 33652749, 2021). "Interleukin (IL)-10, IL-25, IL-33, and thymic stromal lymphopoietin (TSLP) levels were determined using the enzyme-linked immunosorbent assay (ELISA) in nasal polyp tissues." (PMID 32294933, 2020). "We have previously demonstrated that SNPs in the TSLP gene exhibit a gender and/or nasal polyps-dependent risk for CRS." (PMID 31768185, 2019). "This study aimed to measure the expressions of IL-17RB, ST2 and TSLPR, receptor of IL-25, IL-33, and TSLP respectively, on myeloid DCs in nasal polyps (NP) and evaluate their association with local Th2 inflammation and disease severity in patients with NP." (PMID 30519393, 2018). "From this perspective we may conclude that TSLP can be a prominent factor in nasal polyposis associated Th2 skewing." (PMID 27050744, 2016). "Overexpression of TSLP has been shown to be associated with the development of nasal polyps." (PMID 24573880, 2014). "Furthermore, a deficiency of Treg cells and increase in TSLP in nasal polyps may play an important role in the enhancement of the severity of Th2 inflammation in nasal polyps and the persistence and growth of NP." (PMID 25379119, 2014). "The present study revealed a significant difference in TSLP expression levels between nasal polyp tissue and control nasal mucosa across all of the patient subgroups, whereas no such difference was observed in TSLPR expression." (PMID 39940994, 2025). "CM326 is a humanized anti-TSLP monoclonal antibody in phase 2 development in China for chronic rhinosinusitis with nasal polyps (NCT06372678)." (PMID 41409758, 2025). "Using epithelial cells from human nasal tissue explants, authors demonstrated that IL-33 and thymic stromal lymphopoietin (TSLP) is produced during chronic rhinosinusitis with nasal polyps, perpetuating airway Th2 inflammation response." (PMID 40005560, 2025). "This review explores the roles of TSLP signaling in the pathogenesis of chronic rhinosinusitis with nasal polyps and considers the therapeutic potential of targeting TSLP signaling for the treatment of this condition." (PMID 40919679, 2025). "It has been demonstrated that prolonged incubation of nasal polyp (NP) extracts with TSLP generated two main fragments corresponding to TSLP1-97 and TSLP98-132, which remained linked through disulfide bonds as a dimerized form." (PMID 38612858, 2024). "Both IL-33 and TSLP are abundantly present in nasal polyp tissues and are influential in the inflammatory pathways as demonstrated in non-human studies." (PMID 38680486, 2024). "The airway epithelium actively influences immune responses by secreting alarmins such as TSLP, which, when released from nasal polyps, provokes a heightened IL-5 response from mast cells." (PMID 38680486, 2024). "Alarmins are detected in nasal polyps, with TSLP specifically being elevated in CRS with nasal polyp compared to the nasal mucosa of healthy controls." (PMID 38540714, 2024). "TSLP mRNA expression significantly increased in eosinophil-rich nasal polyps compared with eosinophil-poor uncinate tissues from the same patients with ECRS." (PMID 35892679, 2022). "In the end, it should be noted that Nasal fibroblast produces TSLP, and its expression is increased in nasal polyps and allergic rhinitis." (PMID 35264183, 2022). "The viral RNA analog poly I:C, TLR3 ligand was reported to induce TSLP in nasal polyp epithelial cells or bronchial epithelial cells in severe eosinophilic asthma." (PMID 35892679, 2022). "S. aureus binding to TLR 2 directly induces the release of epithelial cell-derived cytokines and promotes the expression of TSLP, IL-5, IL-13, and IL-33 in nasal polyp tissue." (PMID 35878202, 2022). "In epithelial cells of nasal polyps (eosinophil-rich areas), TSLP, IL-25, and IL-33 were higher than in those of uncinate process tissues (eosinophil-poor areas)." (PMID 32085629, 2020).
nasal polyps (continued). "Although Alternaria and HDM induced IL-33 and TSLP production from nasal epithelial cells, the concentration of these two chemical mediators in cultured media was much lower than that of nasal polyp tissues." (PMID 32294933, 2020). "IL-25 is upregulated in nasal polyps and increases thymic stromal lymphopoietin (TSLP)-induced Th2 cell expansion." (PMID 29564208, 2018). "Nasal polyps from patients with CRS have elevated levels of CysLTs, IL-33, TSLP, and IL-4 and multiple groups have shown that ILC2s are enriched in nasal polyps, especially eosinophilic polyps, compared to control tissue." (PMID 28959799, 2017). "TSLP expression is increased in nasal polyps from CRS and AERD patients, AR patient nasal tissue, and in asthmatic airway epithelial cells (with levels positively correlating with disease severity)." (PMID 28959799, 2017). "Our data show that epithelial cells from nasal polyps exposed to poly(I:C) produce a significantly higher amount of TSLP than the inferior turbinate epithelium from healthy individuals both at the mRNA and protein level." (PMID 27050744, 2016). "The TLR3 agonist and viral analogue poly(I:C) induced TSLP mRNA 13.0 ± 3.1 fold (p < 0.05) and protein expression by 12.1 ± 2.3-fold (p < 0.05) higher in epithelium isolated from nasal polyposis patients than in epithelium form healthy controls." (PMID 27050744, 2016). "Here we have shown a poly(I:C)-specific induction of TSLP in epithelium from nasal polyposis patients that is much stronger than the induction detected in epithelium from healthy controls." (PMID 27050744, 2016). "The 487-fold induction seen for TSLP in nasal polyposis is much stronger that the induction seen for IL-6 and IL-8 in healthy epithelium and furthermore the induction of IL-6 or IL-8 is not affected by the diseased state." (PMID 27050744, 2016). "Nonetheless, more clinical trials are ongoing to evaluate tezepelumab efficacies in other TSLP-mediated allergic, inflammatory, and autoimmune disorders that include severe chronic rhinosinusitis with nasal polyposis, chronic obstructive pulmonary disease, and chronic spontaneous urticaria." (PMID 39726595, 2024). "Ongoing research may confirm the role of therapeutic targeting of TSLP with monoclonal antibodies such as tezepelumab in chronic rhinosinusitis with nasal polyps." (PMID 37628907, 2023). "In contrast, an inflammatory role of IL-22 was described in CRS, indicating that IL-22/IL-22Ra1 axis promotes thymic stromal lymphopoietin (TSLP) production under a type-2 microenvironment in airway epithelial cells, potentially contributing to the development of nasal polyps." (PMID 35455762, 2022). "The positive feedback loop between IL-33 and TSLP and their receptors might facilitate the Th2-skewed inflammation in eosinophilic chronic rhinosinusitis with nasal polyps." (PMID 30123216, 2018). "Our data now show that there could be an additional role for viruses that through specific induction of TSLP in nasal polyposis epithelium would be able to contribute to a Th2-skewed environment in polyps." (PMID 27050744, 2016). "In support of this hypothesis, large numbers of Type 2 ILCs are present in nasal polyps and high levels of TSLP have been identified suggesting a key role for this cytokine in polyp pathogenesis." (PMID 25379119, 2014). "In a human study, focusing on nasal polyposis, it was reported that high expression of TSLP in nasal polyps strongly correlated to eosinophils and IgE suggesting a potential role for TSLP in the pathogenesis of nasal polyps by regulating Th2 type and eosinophilic inflammation." (PMID 22838633, 2012). "Therapeutically, investigation of TSLP inhibitors in non‐Th2 inflammatory phenotypes is warranted given their broad‐spectrum mechanisms might provide novel therapeutic pathways for mixed or neutrophilic chronic rhinosinusitis with nasal polyps." (PMID 41178615, 2025).
nasal polyps (continued). "Therefore, the higher expression of P-gp in nasal polyps could be related to the hypersecretion of TSLP and IL-5 in CRSwNP patients." (PMID 35264183, 2022). "We report that epithelial cells derived from nasal polyps of patients with CRSwNP release TSLP and IL-25 when specifically stimulated by poly(I:C), while they could not be activated by the stimulation with Dermatophagoides pteronyssinus or Aspergillus fumigatus extracts." (PMID 28127565, 2016). "By inhibiting P‐gP, verapamil is capable of blocking many inflammatory mediating cytokines that contribute to the formation of nasal polyps (NP), including IL5, IL6 and thymic stromal lymphopoietin (TSLP), ultimately leading to TH2 production." (PMID 41090403, 2026). "Enriched blood and nasal polyp ILC2 cultured with TNF demonstrated a time- and dose-dependent production of IL-5 and IL-13, which was further enhanced in the presence of TSLP or IL-33 in vitro." (PMID 38540714, 2024). "In nasal polyp tissue, S. aureus can directly induce the release of the epithelial cell-derived cytokines TSLP and IL-33 by binding to TLR 2, thereby potentially propagating the expression of type 2 cytokines IL-5 and IL-13 in nasal polyp tissue." (PMID 35878202, 2022). "In this manuscript we explore the reactivity of epithelial cells isolated from nasal polyps and healthy controls to a broad range of TLR agonists in their ability to induce the expression and production of TSLP, IL-25, and IL-33." (PMID 27050744, 2016). "Further work has shown that ILC2 from nasal polyps produce IL-13 in a GATA3-dependent manner after culture with IL-2, IL-33 and TSLP." (PMID 24876829, 2013). "Subsequently, a role for TSLP in activation of ILC2 was demonstrated as purified human peripheral blood and nasal polyp ILC2 cultured with TSLP and IL-33 displayed enhanced IL-4, IL-5, and IL-13 production above IL-33 alone." (PMID 24876829, 2013). "The expression levels of IL-25 and TSLP are higher in nasal polyps of patients with ECRS than in normal nasal mucosa." (PMID 39015572, 2024). "Interestingly, the level of TSLP enhancement between the control and the DUSP-1 knock-down strain was comparable to that between nasal polyp and healthy control epithelium." (PMID 27050744, 2016). "At the protein level, we show that upon poly(I:C) challenge increased TSLP secretion is only seen in nasal polyposis epithelium and not in healthy epithelium." (PMID 27050744, 2016). "This study investigated whether TSLP and TSLPR expression in peripheral blood or nasal polyps could provide a valuable approach for the molecular phenotyping of patients with chronic rhinosinusitis with nasal polyps (CRSwNP)." (PMID 39940994, 2025). "Moreover, we see only the increased TSLP induction and no increased induction of the other Th2-skewing mediators IL-25 and IL-33 in nasal polyposis epithelium." (PMID 27050744, 2016). "It has been reported that the expression of TSLP and TSLPR was upregulated in eosinophilic but not non-eosinophilic nasal polyps and epithelial cells from CRSwNP patients compared to controls." (PMID 39940994, 2025). "Thus, the aim of the present study was to investigate any relationship between abnormal DNA methylation status of a CpG island in the TSLP gene and pathogenesis of CRS with or without nasal polyps." (PMID 31768185, 2019). "Examination of nasal polyps from individuals with nonsteroidal anti-inflammatory drug (NSAID) aspirin-exacerbated respiratory disease (AERD)—NERD and those with chronic rhinosinusitis (CRS) without NERD/AERD showed that TSLP mRNA expression was significantly increased in NERD/AERD." (PMID 37628907, 2023).
psoriasis (40 papers, 2009 to 2026). An autoimmune condition characterized by red, well-delineated plaques with silvery scales that are usually on the extensor surfaces and scalp. "Multiple lines of evidence support the role of two classically AD-linked cytokines, TSLP and IL-31 in psoriasis." (PMID 35321329, 2022). "The development of IL-23-associated autoimmune disease psoriasis has recently been linked to overexpression of TSLP in keratinocytes from patient skin samples." (PMID 32849527, 2020). "These novel findings extend the role of TSLP to the regulation of keratinocyte proliferation in psoriasis‐like progression, which is an important hallmark in psoriasis." (PMID 31556482, 2019). "Confirming that endogenous TWEAK activity had a function in TSLP and IL-19 production in vivo, gene-deficient mice exhibited reduced expression of these molecules in the skin in the AD and psoriasis models, respectively." (PMID 28530223, 2017). "As the use of TNF-α inhibitors is associated with an elevated risk of infections, targeting TSLP may be more suitable for treating psoriasis." (PMID 38666958, 2024). "Firstly, serum levels of TSLP are significantly elevated in patients with psoriasis, and its concentrations are positively correlated with the PASI score." (PMID 38666958, 2024). "As a ligand for Toll-like receptors 7/8, imiquimod induced the release of TSLP in the skin lesions as a critical mediator of the pathogenesis of IMQ induced psoriasis." (PMID 39726595, 2024). "The injection of antibodies against TSLP in psoriasis-like mouse models has resulted in the regression of psoriasis, reduced epidermal hyperplasia, decreased VEGF α expression, and the epidermal inhibition of STAT-5 phosphorylation." (PMID 38666958, 2024). "TSLP is produced by mutant bulge hair follicle stem cells and DCs, both dermal and myeloid, in patients with psoriasis." (PMID 38666958, 2024). "TAVO101 exhibited a trend of better efficacies than tezepelumab in reducing skin lesions in the psoriasis model, likely owing to the slightly more potent neutralization of skin TSLP than tezepelumab dosed at the same levels." (PMID 39726595, 2024). "Serum TSLP has been reported to be elevated in psoriasis patients with a significant correlation to disease severity." (PMID 37546687, 2023). "TSLP is a proallergic keratinocyte-derived cytokine, which has been described to induce dendritic cell maturation and IL-23 production in psoriasis pathogenesis." (PMID 37546687, 2023). "Recent studies demonstrated that IL-31 and TSLP appear to be partially involved not only in the pathogenesis of psoriasis, but also in the induction of itch in psoriasis." (PMID 35173615, 2022). "CB2R didn't participate in the induction of itch in psoriasis by regulating the expression of IL-31, thymic stromal lymphopoietin (TSLP) and mast cells in mouse skins." (PMID 35173615, 2022). "The role of multiple pruritic mediators have been investigated in psoriasis, including neuropeptides, nerve growth factor, IL-31, and TSLP." (PMID 35321329, 2022). "Collectively, these data suggested that CB2R didn’t participate in the induction of itch in psoriasis by regulating the expression of IL-31, TSLP and mast cells in mice." (PMID 35173615, 2022). "Local injection of TSLP antibodies in the psoriasis-like mouse model led to skin inflammation regression, reduced epidermal hyperplasia, decreased vascular endothelial growth factor α expression, and epidermal inhibition of STAT-5 phosphorylation." (PMID 34249003, 2021). "In contrast, TSLP expression level was increased in lesional areas with psoriasis in both compartments, IFE and hair follicles." (PMID 31556482, 2019). "Overproduction of TSLP was found in keratinocytes of human AD skin lesions and in psoriasis patients." (PMID 31556482, 2019). "We next analyzed the expression of STAT3 and STAT5 phosphorylation (p‐STAT3, p‐STAT5) by immunofluorescence in ear sections of psoriasis‐like mice treated with anti‐TSLP or IgG." (PMID 31556482, 2019).